POSTN (periostin)
Diseases named in the same sentence as POSTN in open-access papers (continued):
Sharing a sentence is not in itself a finding about the gene and the disease.
renal cell carcinoma (12 papers, 2017 to 2024). "Periostin has been linked to renal cell carcinoma, where it promotes migration and invasion via the integrin/focal adhesion kinase/c-Jun N-terminal kinase pathway." (PMID 32511227, 2020). "Elevated periostin expression was also detected in biopsies of renal cell carcinoma (RCC) and was associated with increased tumor aggressiveness and poor prognostic survival." (PMID 28536691, 2017). "The overexpression of POSTN has also been verified to promote EMT in renal cell carcinoma cells by activating the IKL/AKT/mTOR pathway." (PMID 38280891, 2024). "A recent study of renal cell carcinoma cells also demonstrated that POSTN overexpression increased the activity of MMP-2 and MMP-9." (PMID 35163164, 2022). "It has been shown that the different isoforms of periostin are expressed in various cancer, including pancreatic, colon, breast, lung, and renal cell carcinoma (RCC)." (PMID 36224629, 2022). "This research focused on the detailed mechanisms study of periostin (POSTN) overexpression in renal cell carcinoma (RCC) invasion and migration." (PMID 34093819, 2021). "In this sense, POSTN has been shown to increase the activity of matrix metalloproteinase-2 and metalloproteinase-9 and promote migration and invasion in renal cell carcinoma cells." (PMID 29946533, 2018). "POSTN is significantly expressed in renal cell carcinoma (RCC)." (PMID 35281822, 2022). "The authors suggest that POSTN expression in cancer epithelial cells may contribute to sarcomatoid differentiation and a more aggressive behavior of renal cell carcinoma." (PMID 29946533, 2018). "In renal cell carcinoma (RCC), POSTN emerges as a key regulator, where its knockdown significantly suppresses epithelial-mesenchymal transition (EMT) through the IKL/AKT/mTOR pathway." (PMID 38375508, 2024). "In this study, we investigated the expression of POSTN in several RCC cells, which POSTN was high-expressed in RCC cells, suggesting POSTN may be an oncogene of renal cell carcinoma." (PMID 34093819, 2021).
cholangiocarcinoma (11 papers, 2010 to 2025). A carcinoma that arises from the intrahepatic biliary tree (intrahepatic cholangiocarcinoma) or from the junction, or adjacent to the junction, of the right and left hepatic ducts (hilar cholangiocarcinoma). "The cholangiocarcinoma study integrated analysis of 85 PANoptosis-related genes to uncover POSTN+ CAFs as key resistance orchestrators spatially linked to immunosuppressive TAMs and PD-L1/2, while developing the clinically actionable PANRS model (POSTN/SFN/MYOF/HOGA1/PECR)." (PMID 40693266, 2025). "Serum POSTN was identified as an independent prognostic factor suggesting that it could be used as a marker of poor prognosis in patients with cholangiocarcinoma." (PMID 29946533, 2018). "PI3K activation in response to integrin signalling is well documented in cancer, and there are some reports of Akt activation leading to tumour cell invasion in response to integrin-mediated periostin signalling in epithelial tumours, eg integrin α5β1 in cholangiocarcinoma." (PMID 25345775, 2015). "POSTN as well, which is expressed in α-SMA+CAFs but not in normal/cirrhotic liver or hepatocellular carcinoma, is involved as a prognostic factor in CCA because it is correlated with a shorter 5-year survival time in post-resected cholangiocarcinoma." (PMID 36362726, 2022).
cyst (11 papers, 2017 to 2025). A sac-like closed membranous structure that may be empty or contain fluid or amorphous material. "High expression of periostin was associated with acceleration of cyst growth and fibrosis in PKD." (PMID 34768419, 2021). "Our cross-sectional design limits assessment of temporal changes in periostin levels during cyst evolution." (PMID 41156134, 2025). "In contrast, periostin concentrations were low in patients with cyst involution or after nephrectomy." (PMID 41156134, 2025). "Future longitudinal studies, incorporating serial periostin measurements and ultrasound-based monitoring of cyst involution, are necessary to delineate periostin’s temporal dynamics and prognostic value." (PMID 41156134, 2025). "In ADPKD, persistently elevated periostin parallels progressive cyst growth, whereas in MCDK, periostin is also elevated but associated with an opposite clinical course—cyst involution and renal atrophy." (PMID 41156134, 2025). "This unique pattern positions periostin as a potential biomarker of cyst activity and involution in cystic renal diseases." (PMID 41156134, 2025). "Our study demonstrates a significant upregulation of POSTN mRNA and protein levels in cyst tissues compared to the control group, suggesting a potential role for periostin in the pathogenesis or progression of cysts." (PMID 39728072, 2024). "In ADPKD, POSTN is highly expressed in cyst-lining epithelial cells and accumulates within the matrix surrounding the cysts." (PMID 39728072, 2024). "POSTN mRNA and protein levels of POSTN were upregulated in the cysts’ tissues compared to the control group, indicating POSTN’s possible involvement in cyst pathogenesis or progression." (PMID 39728072, 2024). "As periostin is known to increase cell proliferation in ADPKD cyst epithelial cells, we estimated in vitro the physiological relevance of the periostin cleavage by MMP9 by quantifying the proliferation of IMCD-3 cell line, which do not produce MMP9." (PMID 38039285, 2023). "In a microarray analysis of cultured human ADPKD cyst epithelial cells, periostin mRNA was markedly overexpressed compared with normal human kidney cells." (PMID 36120538, 2022). "Periostin binds to αVβ3 and αVβ integrins, activates the integrin-linked kinase (ILK), a component of focal adhesion plaques, and promotes in vitro cyst growth." (PMID 36120538, 2022). "Increased renal expression of the matricellular protein periostin is accompanied by upregulation of vimentin, which leads to increased mTOR activity, cell proliferation, cyst growth, interstitial fibrosis and acceleration of decline in renal function." (PMID 34206927, 2021). "In aneurysmal bone cyst (ABC) and simple bone cyst, the fibrous stroma and reactive bone within the cyst wall was positive for periostin." (PMID 30202513, 2018). "The hypothesis of our study is that periostin can be one of the markers of cyst progression in kidneys." (PMID 41156134, 2025). "Indeed, children with complete cyst involution or surgical removal of the dysplastic kidney (group B) likely exhibit reduced renal parenchymal mass and diminished periostin production." (PMID 41156134, 2025). "The reduction in periostin levels following cyst regression suggests a loss of active fibrotic remodeling rather than a direct suppression of periostin synthesis." (PMID 41156134, 2025). "In this context, our study focused on periostin concentrations in children aged 1–5 years with MCDK, demonstrating significantly elevated serum periostin (239.1 ng/mL) in patients with cystic kidneys compared to 77.7 ng/mL in children with cyst involution or post-nephrectomy." (PMID 41156134, 2025). "The β3 integrin co-localized with periostin at the base of the cyst." (PMID 38039285, 2023). "Additionally, periostin/αv/ILK (integrin-linked kinase) and periostin/αvβ3/AKT/mTOR signaling pathways both aggravated the growth of cyst epithelial cells in autosomal dominant polycystic kidney disease (ADPKD)." (PMID 36611844, 2022).
cyst (continued). "Periostin is one of the most highly expressed proteins in human autosomal dominant polycystic kidney disease (ADPKD), where it correlates with cyst expansion and fibrotic progression." (PMID 41156134, 2025). "The mechanisms governing cyst regression in MCDK remain incompletely understood, and the regulation of periostin in this process warrants further investigation." (PMID 41156134, 2025). "Retention cyst tissues demonstrated an increase in POSTN mRNA and protein expression, whereas serum periostin levels remained consistent with those observed in the control group." (PMID 39728072, 2024). "The aim of our research was to assess the concentration of serum periostin (sPOST) in children with MCDK and the presence of cysts on ultrasound examination and to compare them to children with MCKD and cyst involution, as well as to healthy children as a control group." (PMID 41156134, 2025). "While research specifically on POSTN in nasal cysts is scarce, insights from studies on autosomal dominant polycystic kidney disease (ADPKD) provide valuable context for understanding its potential functions in cyst formation and progression." (PMID 39728072, 2024). "Serum levels of POSTN showed no significant alternation, indicating that the increased expression is localized to the cyst tissue itself." (PMID 39728072, 2024). "Thus, periostin may function as a context-dependent regulator: persistently high levels, as seen in ADPKD, may perpetuate fibrotic remodeling and cyst proliferation, whereas transient expression in MCDK may facilitate repair and eventual regression." (PMID 41156134, 2025). "Notably, in our cohort, involution occurred despite elevated periostin, suggesting that periostin may not be the direct driver of cyst persistence but rather a marker of tissue remodeling." (PMID 41156134, 2025).
inflammatory bowel disease (11 papers, 2016 to 2026). A spectrum of small and large bowel inflammatory diseases of unknown etiology. "Augmented periostin expression has also been associated with chronic inflammation such as in inflammatory bowel disease (IBD)." (PMID 34512647, 2021). "Periostin is also upregulated in other chronic inflammations such as inflammatory bowel disease and rheumatoid arthritis." (PMID 35707463, 2022). "Periostin mediates intestinal inflammation through the activation of NF-κB signaling, which suggests that periostin is a potential therapeutic target for inflammatory bowel disease." (PMID 26890265, 2016). "That periostin mediates intestinal inflammation via the activation of NF-κB pathway, which suggests that periostin may be a potential therapeutic target for inflammatory bowel disease has been reported." (PMID 28525373, 2017). "The precise role of periostin, an extra-cellular matrix protein, in inflammatory bowel disease (IBD) is unclear." (PMID 33737520, 2021).
osteoporosis (11 papers, 2020 to 2025). A condition of reduced bone mass, with decreased cortical thickness and a decrease in the number and size of the trabeculae of cancellous bone (but normal chemical composition), resulting in increased fracture incidence. "We propose that the dysregulation of Periostin secretion in osteoporosis is caused by chronic inflammation in osteoporosis." (PMID 39940700, 2025). "Increased expression of IL-6 in patients with osteoporosis was detected; therefore, the effect of cytokines on Periostin splice variant expression was evaluated here." (PMID 39940700, 2025). "The aim of the following study was to determine the splice variants of Periostin expressed in human osteoblasts and Periostin’s function in the pathophysiology of osteoporosis." (PMID 39940700, 2025). "The expression of splice variants in patients with osteoporosis was found to be like that observed in patients with normal bone density, with Periostin isoform 4 identified as the dominant splice variant." (PMID 39940700, 2025). "POSTN, which is associated with inflammation, has also been shown to affect NF-κB in osteoblasts, suggesting its involvement in osteoporosis." (PMID 38020106, 2023). "POSTN is also expressed in bone cells and osteoblasts, regulating osteoblast and bone formation and is associated with osteoporosis via the sclerostin-mediated Wnt/β-catenin pathway." (PMID 38020106, 2023). "In huRANKL-overexpressed mice, cathepsin K (Ctsk) limited bone formation and increased bone fragility by preventing periostin generation, which offers an underlying mechanism for osteoporosis in PMW." (PMID 36611844, 2022). "Because of its interaction with IL-6, Periostin could also potentially be used as a marker of chronic inflammation in patients with known osteoporosis, to allow a causal therapeutic approach." (PMID 39940700, 2025). "An anti-Periostin antibody for osteoporosis could exploit the expression of splice variants in bone and target Periostin-4 and -3." (PMID 39940700, 2025). "Periostin in bone is, thus, closely linked to inflammation, suggesting sequential expression during fracture healing and pathologically increased expression during chronic inflammation in osteoporosis." (PMID 39940700, 2025). "In addition to the effect of cytokines such as IL-6 on the formation of total Periostin, the impact on the splice variants formed is of interest in assessing the function of Periostin in bone during inflammation and osteoporosis." (PMID 39940700, 2025). "Therefore, the significant correlation of Periostin with age suggests at least an association with osteoporosis." (PMID 39940700, 2025). "Therefore, understanding the role of POSTN, which is involved in bone metabolism, inflammation, and aging, is expected to provide insights into the development of osteoporosis caused by the imbalance in bone metabolism." (PMID 38020106, 2023). "Therefore, serum periostin and its encoding gene could be informative clinical tools for predicting the risk of osteoporosis and vertebral fractures in Chinese postmenopausal women." (PMID 35327993, 2022). "Besides, chronic GC treatment is associated with osteoporosis, while Periostin could promote bone regeneration." (PMID 31918919, 2020). "The aim of this study was to further elucidate the mechanisms behind the pathophysiology of osteoporosis, focusing on the effect of Periostin on osteogenic differentiation and inflammatory bone reactions." (PMID 39940700, 2025). "The bone-resorbing properties of Periostin and its interaction with IL-6 open up new possibilities for the pharmacological treatment of osteoporosis." (PMID 39940700, 2025). "Nevertheless, the observed trend of elevated Periostin protein expression in osteoblasts of patients with regular bone density, in comparison to those with osteoporosis, is also apparent in this context." (PMID 39940700, 2025).
osteoporosis (continued). "According to current knowledge and our understanding of the function of Periostin, it should be detectable at elevated levels in acute fracture healing and osteoporosis compared to an age-adjusted normal value." (PMID 39940700, 2025). "The increased secretion of Periostin in osteoblasts from donors with osteoporosis suggests a role for Periostin in the pathogenesis of the disease." (PMID 39940700, 2025). "Excitingly, this relationship was reversed when monitoring Periostin secretion, since osteoblasts from osteoporosis patients secreted significantly more Periostin." (PMID 39940700, 2025). "OPG secretion with the addition and inhibition of Periostin was used to demonstrate its effect on relevant osteoporosis parameters." (PMID 39940700, 2025). "Not only its effect on bone density in osteoporosis, but also on Periostin serum levels, would be of interest." (PMID 39940700, 2025). "We found an altered relationship between Periostin expression and secretion when categorising patients with osteoporosis and normal bone density." (PMID 39940700, 2025). "Although Periostin expression is reduced, its secretion is increased, likely due to chronic inflammation of the bone in osteoporosis." (PMID 39940700, 2025). "Based on these findings, there is a possibility that POSTN is also involved in osteoporosis resulting from aging." (PMID 38020106, 2023). "Here, we isolated bone marrow skeletal stem cells (BMSCs) derived from an ovariectomy (OVX)-induced osteoporosis rat model and the effects of periostin on BMSCs derived from OVX rats (OVX-BMSCs) were assessed." (PMID 34591063, 2021). "Since we found a reduction in Periostin expression in rBMSCs derived from the osteoporosis model rats, we investigated its effects on rBMSC osteogenic differentiation." (PMID 34591063, 2021). "In another study, the anti-osteoporosis drug teriparatide, an anabolic drug that promotes bone remodeling in patients with osteoporosis, was found to trigger the secretion of POSTN to promote bone formation and counteract osteoporosis." (PMID 34513869, 2021). "Here, we demonstrated the active role of POSTN in 17β-E2-mediated osteogenic differentiation, revealing POSTN as a candidate target for the prevention and treatment of osteoporosis." (PMID 32420385, 2020). "Thus, POSTN could be a novel target gene for anti-oestrogen-deficiency-related osteoporosis." (PMID 32420385, 2020). "In the pathogenesis of osteoporosis, these mechanisms of bone regeneration could be dysregulated, resulting in pathological, permanently increased secretion of Periostin." (PMID 39940700, 2025). "No change in the expression pattern of Periostin splice variants was detected in osteoblasts from osteoporosis patients compared to osteoblasts from patients with normal bone density." (PMID 39940700, 2025). "This would be dysregulated in osteoporosis with increased IL-6 and Periostin expression and could also be used therapeutically to slow inflammation and bone loss." (PMID 39940700, 2025). "The collective findings illustrate a correlation between Periostin and patient age, which may contribute to the expression of Periostin in osteoporosis." (PMID 39940700, 2025). "The expression of both Periostin mRNA and protein was significantly, or at least in tendency, increased in osteoblasts from patients with normal bone density compared to osteoblasts from patients with osteoporosis." (PMID 39940700, 2025). "Since Periostin is secreted by osteoblasts, and these have a substantial impact on bone homeostasis and osteoporosis, we investigated the expression of Periostin in human osteoblasts and its effects on osteogenic differentiation as well as OPG and IL-6 secretion." (PMID 39940700, 2025). "However, Periostin was secreted in significantly higher amounts in osteoblasts from patients with osteoporosis." (PMID 39940700, 2025). "Interrupting the vicious cycle between Periostin and IL-6 or TGFβ could be a potential target for new therapeutics in osteoporosis." (PMID 39940700, 2025).